IFNG (interferon gamma)
Diseases named in the same sentence as IFNG in open-access papers (continued):
Sharing a sentence is not in itself a finding about the gene and the disease.
tumor (continued). "The statistical significance (Mann–Whitney t-test) of the tumor volume of groups treated with SFV/Luc (sc.SFV/Luc+Pam3) and SFV/IFNg (s.c.SFV/IFNg+Pam3) on the last day (day 17) reached the probability level of p = 0.2103 (nonsignificant)." (PMID 34835178, 2021). "The aim of this study was to investigate the irradiation effect on IFNγ-mediated STAT1 and STAT3 phosphorylation and genes expression such as PD-L1 and anti-apoptosis genes in EGFR-positive tumor cells to augment CD8+ T cells cytotoxicity against NSCLC." (PMID 34685495, 2021). "Th1 produce type I cytokines, including IL-2 and IFNγ, facilitating optimal expansion, trafficking, and effector functions of CD8+ T cells, thereby reducing tumor growth and progression." (PMID 33535484, 2021). "Different from functionally killing tumor cells and cancer stem cells (CSCs) in the bloodstream, NK cells show reduced cytotoxicity on transformed cells in the TME with producing less IFNγ." (PMID 34434889, 2021). "Immunotherapy-activated CD8+ T cells secreted interferon gamma (IFNγ), and then downregulated SLC7A11 in tumor cells and finally promoted cancer cell lipid peroxidation and ferroptosis." (PMID 34722530, 2021). "By means of IFNγ production, expression of MHC class I tumor-related antigens is upregulated, allowing swift recognition and elimination by production of cytotoxic granzymes and perforin." (PMID 33916646, 2021). "They found that interferon gamma (IFNγ) released from CD8+ T cells downregulated the expression of SLC3A2 and SLC7A11, impaired the uptake of cystine by tumour cells, and promoted ferroptosis." (PMID 34858857, 2021). "IFNγ promotes production of IL-10 and TGF-β by MDSCs, and these cytokines, in the presence of tumor antigen-stimulated T cells, increase MDSC-induced development of immunosuppressive Tregs." (PMID 33801234, 2021). "An increase was detected in the ratios of CD8+IFNγ+/CD4+FoxP3+ T cells and CD8+IFNγ+/CD11b+Ly6G+ cells in pHIFU + ICI-treated tumours relative to controls." (PMID 34229458, 2021). "Treatment of MCT inhibitors blocked lactate export by cancer cells and these inhibitors synergized with anti-PD-1 therapy to profoundly promote IFNγ production by CD8+ T cells, thereby reducing tumor burden." (PMID 34359884, 2021). "The multiple roles of ferroptosis in tumor immunity is attracting intense interest, which mainly focuses on CD8+ T cells that induce ferroptosis of cancer cells through secreting interferon gamma." (PMID 34527677, 2021). "In another study, IFNγ administration reversed SEREX-defined self-Ag-mediated increase in generation/activation of Tregs, resulting in lower tumor incidence and metastasis in vivo." (PMID 33801234, 2021). "The impact of C-7 on the levels of various cytokines (IFNγ, TNF, IL-6, and IL-10) and the chemokine CXCL10 was assessed in 1-day co-culture supernatants of dissociated CRC tumor cells and autologous PBMC." (PMID 34771609, 2021). "Analysis of the tumor EV-educated macrophages (TEMs) showed secretion of a variety of factors including CXCL1, CTLA-4, IFNG, OPN, HGF, TGFB, and CCL19 capable of remodeling the surrounding tumor stroma and immune infiltrate." (PMID 34298673, 2021). "Generally, cytotoxic CD8+-T cells are antigen-processed and have ability to eliminate tumor cells, whereas CD4+ T helper 1 cells (Th1) activate cytotoxic T cells to secrete interleukin-2 (IL2), interferon gamma (IFNγ), and tumor necrosis factor." (PMID 34434889, 2021). "Production of proinflammatory cytokines, in particular interferon-gamma (IFN-γ) and interleukin-2 (IL-2), was also observed in a subset of ParvOryx01 patients’ tumor samples." (PMID 34452286, 2021). "Studies have shown that IFNγ produced by immune cells to combat harmful material is significantly reduced in the presence of MDSC-generated NO, indirectly promoting tumor growth and progression." (PMID 34063667, 2021).
tumor (continued). "To further characterize the functionality and heterogeneity of the CAR T cell pool within the CAR+ BE2 tumor, we performed IHC for CD19, CAR RNA FISH combined with either GZMB or IFNγ RNA FISH on several sequential slides from the same tissue block." (PMID 34155235, 2021). "In this model, tumor PD-L1, among other proteins, is upregulated by CTL-derived IFNγ, which is thought to prevent CTL-mediated killing." (PMID 33670921, 2021). "Most importantly, the sudden effects on NF-kB pathway correlated to a strong reduction of IFNγ and CD73 in CD8+ cells, as NF-kB activation is known to increase the number of tumor-specific IFNγ-producing CD8+ T cells and is required for tumor elimination." (PMID 34070750, 2021). "This interaction inhibits CD4+/CD8+ tumor-infiltrating T-lymphocytes (CD4+/CD8+ TILs), which results in a decrease in cytokines, such as Interleucin-2 (IL-2), interferon gamma (IFN-γ) and tumor necrosis factor (TNF)." (PMID 34943606, 2021). "Several other candidate biomarkers have been suggested including tumor infiltrating lymphocytes, CD8 + T cell density in the TME, IFNγ signaling, Wnt/β-catenin signaling and genetic signatures." (PMID 34208788, 2021). "High tumor MHC-I expression was strongly correlated with CD8 T-cell infiltration and activity, and with expression of IFNγ-upregulated genes (“IFNγ signatures”) in multiple studies." (PMID 34201655, 2021). "The primary tumor responded to PD1, OX40, and PD1+CTLA4 treatment with increased production of IFNg, and accompanying increases in the IFN-regulated chemokine IP-10 (CXCL10) and the proinflammatory chemokine RANTES (not shown)." (PMID 34221953, 2021). "Both treatments, the SFV/IFNg vector alone or in combination with TLR2/1 Pam3 ligand, revealed inhibition of tumor growth in the orthotopic model." (PMID 34835178, 2021). "Th1 cells produce interferon gamma (IFN-γ) and tumor necrosis factor alpha (TNF-α), which promote cellular immunity to initiate effective anti-tumor response." (PMID 33639614, 2021). "GZMB, PRF1 and IFNγ are activation markers and PD-1 is the exhaustion marker of CD8+ T cells, whereas GZMB and PRF1 are major hydrolytic enzymes leading to tumor apoptosis." (PMID 34680466, 2021). "Platelets can induce tumor cells to release soluble NKG2D ligands to avoid the detection by NK cells and inhibit producing inflammatory cytokine (IFNγ)." (PMID 34540678, 2021). "Upregulation of NPTX2 in cold tumor negatively correlated with the expression of CD8A, GZMB, and IFNG, and knockdown of NPTX2 increased the production of CCL4." (PMID 34258887, 2021). "ILC1s possess Th1 characteristics that include (i) pro-inflammatory and anti-tumour functions, (ii) expression of the master regulatory transcription factor TBET and (iii) production of IFNγ upon activation." (PMID 34885021, 2021). "Accordingly, the co-treatment of galunisertib with anti-PD-L1 treatment induced an immune response characterised with elevated T-bet and IFNγ levels in CD4+ T cells, increased GZMB production, along with increased infiltration into the tumours." (PMID 33669775, 2021). "Specifically, we show that a 3-PRE promoter composed from PREs responding to IFNγ, TNFα, and hypoxic stimuli can be employed to restrict CAR expression to the tumor site." (PMID 33514819, 2021). "Probiotic administration in mice resulted in a significant increase in interferon gamma (IFN-γ), Granzyme B and chemokine production in the tumor tissue as well as enhanced CD8+ T cell infiltration, accompanied by a suppression of tumor growth." (PMID 32033490, 2020). "In intracellular cytokine staining, we found more tumor infiltrating CD8+CD44+ T cells generating CD107 and Interferon-gama (IFNγ) in KO mice compared to WT mice when stimulated with PMA plus Ionomycin." (PMID 32477338, 2020). "The main anti-tumor actions of IL-12 are promoted by a specific signaling pathway that includes STAT4 and interferon gamma (IFNG)." (PMID 32973967, 2020).
tumor (continued). "Prominently, we can conclude from our in vitro T cell experiments that tumor derived MDSC carried out the suppression of T cell proliferation and interferon gamma production." (PMID 33247701, 2020). "PDT and FlaB-Vax combination therapy induced efficacious systemic antitumor immune responses for local and abscopal tumor control, with a significant increase in tumor-infiltrating effector memory CD8+ T cells and systemic IFNγ secretion." (PMID 33171765, 2020). "When cocultured in vitro with parental, unmodified tumor cells, splenocytes from mice which received B16-APOBEC3BACTIVE vaccines secreted significantly more interferon gamma (IFNγ) than mice treated with B16-APOBEC3BINACTIVE (p < 0.05)." (PMID 32034147, 2020). "Combination therapy promoted IFNγ production by CD4+ T cells in the tumor and CD8+ T cells in the spleen and granzyme B production by CD8+ T cells in the tumor." (PMID 33256806, 2020). "Treatment with CEA-TCB triggered secretion of pro-inflammatory cytokines (IFNγ, TNFα, IL-2) and several chemotactic molecules (CXCL9, CXCL10, CXCL11, CXCL13) indicating the generation of a highly inflamed tumor microenvironment." (PMID 33330050, 2020). "In HCC, we observed increased expression of several more activation- (IFNG, CD38, IL2RA, TNFRSF9) and exhaustion-related (TIGIT, CTLA4, PDCD1, ENTPD1) genes in tumor MAIT cells." (PMID 32849590, 2020). "Upregulation of IFNγ can promote T cell responses, as well as upregulate MHC class I molecules on tumor cells, increasing their sensitivity to cytotoxic T cells." (PMID 32133005, 2020). "It was shown that IFNγ promotes the expression of PDL1 and PDL2, both on tumor cells and on immune infiltrating cells, and suppresses the effector function of tumor-specific T cells or NK cells through interaction with the immune inhibitory receptor PD1." (PMID 32937860, 2020). "It was also shown that specific antibodies against cytokines TNFα, IFNγ and IL-2, which were co-incubated with Tag7-PBMC, decrease the cytotoxic effect of Tag7-PBMC against tumor cells." (PMID 33291689, 2020). "We found that tumor endothelial cells from agonistic CD40 mAb treated tumors upregulated biological processes such as “inflammatory response”, “response to IFNγ”, “positive regulation of leukocyte chemotaxis” and “positive regulation of TNF production”." (PMID 32231867, 2020). "Intriguingly, 10–40% of each short-term tumor-specific CTL lines displayed CpG methylation at positions −186 and −54 within their IFNγ promoter." (PMID 32194559, 2020). "Each tumor-specific CTL clone was first treated with 5-aza-2′-deoxycytidine for 3 days to induce DNA demethylation, prior to assessing their IFNγ mRNA and protein levels." (PMID 32194559, 2020). "TIDE signature was pressure tested on pre-CPI treatment tumor tissue samples of melanoma patients and in this cohort it performed better in predicting response patterns than PDL-1 levels, TMB, and an IFNγ signature." (PMID 32258034, 2020). "The results showed that the percentage of CD3+CD8-IFNγ+ T cells was increased in each of the tumor-bearing mice groups compared with the healthy mice, whereas the percentage of CD3+CD8+IFNγ+ T cells only increased in mice immunized five times with the vaccine." (PMID 32823603, 2020). "Several other pro-inflammatory targets leading to potentially tumor-toxic effects, such as CCL17, IFNγ, IL1β, and IL6, were increased in tendency." (PMID 32316245, 2020). "Actually, the anti-PD-L1 treatment led to an increase in activated cytotoxic CD4+ T and CD8+ T cells in the TILs (IFNγ+CD4+ T cells and IFNγ+ CD8+ T cells) and resulted in an increased number of TUNEL-positive cells in 4T1-WT tumours." (PMID 32732922, 2020). "A clinicopathological study revealed PD-L1 expression levels in tumor microenvironments compared to levels in tumor cells, demonstrated the correlation between the expression of CD4 and interferon-gamma (IFN-γ), and evaluated prognosis." (PMID 32101576, 2020).
tumor (continued). "Interferon gamma (IFN-γ) and tumor necrosis factor (TNF-α) secreted by activated T-cells can also induce PD-L1 expression on tumor cells and antigen-presenting cells (APCs)." (PMID 32733486, 2020). "Increased CD3+ T-lymphocyte and CD8+ T-cell tumor infiltration in RANK−/− tumors compared with RANK+/+ was confirmed by IHC and the mRNA levels of the cytotoxicity markers, namely Ifnγ and perforin (Prf1) were higher in RANK−/− tumors." (PMID 33303745, 2020). "Another interesting observation is that NRP-1 deficiency in Tregs confers TH1 functions to these cells, including production of IFNγ, thereby influencing other Tregs and CD8+ T cells and stimulating anti-tumor immunity." (PMID 33266104, 2020). "Skeletal muscles are subjected to damaging stimuli, primarily due to cytokines produced by tumor cells, such as IL-6, TNF-α, and IFNγ, responsible for inflammation." (PMID 33158194, 2020). "Consistent with a more pro-inflammatory TME, a higher frequency of tumor-infiltrating CD8+ T cells co-expressing NKG2D, Granzyme B, and IFNγ was observed in bintrafusp alfa-treated animals." (PMID 32373533, 2020). "M1 macrophages secrete interferon-gamma (IFN-γ), which has an anticancerous effect, whereas tumor-infiltrating M2 macrophages are procancerous and are associated with tumor growth and metastasis." (PMID 33457427, 2020). "Specifically, tumor tissue supernatants from WT and GCSFR−/− mice tumors were assessed for the production of IFNγ, IL-10, IL-17A, and IL-4, which are considered general markers of Th1, Tregs, Th17, and Th2 cells, respectively." (PMID 33042110, 2020). "At a later stage of tumor development, when CD4+ Treg cells dominate the tumor-microenvironment, CD4+ Tregs mediate the clonal deletion of these tumor-suppressive KIR+ IFNγ+ CD25+ CD8+ T cells and ensure tumor immune evasion." (PMID 33076479, 2020). "Accordingly, our analysis of a subset of genes that had a significant Z score for similarity to proliferation of tumor cells predicted cell cycle progression through genes such as CDK4, HRAS, IL-4, CSF2, IFNG, IL-6 and STAT3." (PMID 33180876, 2020). "Combination of model tumor specific antigens (gp100/MART-1) formulated as a SLP and αGC in one liposome results in strong activation of CD8+ and iNKT, as measured by IFNγ secretion." (PMID 32536918, 2020). "IL-12 also induces the production of large amounts of IFNγ which itself is cytostatic/cytotoxic, anti-angiogenic and can upregulate MHC I and II expression on tumor cells for enhanced recognition and lysis." (PMID 33178203, 2020). "Because anti‐tumor effects of TNF and IFNγ had been observed in pre‐clinical models, both cytokines were tested in the clinic when recombinant proteins became available." (PMID 31916677, 2020). "An elevated glycolysis rate leads to increased lactic acid production, resulting in its accumulation within the tumor microenvironment (TME), where it blocks IFNγ production and reduces survival of CD8+ T and NK cells in vitro and in vivo." (PMID 33123121, 2020). "In this context, moDCs stimulated with supernatant of tumor cells treated with highly cytotoxic NB-PDT were able to enhance the proliferation and IFNγ production of CD4+ T cells, compared to untreated moDCs." (PMID 32326519, 2020). "As expected, we observed increased levels of the CD8 effector cytokine IFNγ in mice receiving CAR-T cells, which significantly correlated with decreased tumor burden (p-value = 0.036)." (PMID 32849651, 2020). "Mice treated with G100 also had significantly higher levels of tumor antigen-specific CD4 and CD8 T cells that secrete IFNγ and IL2 after in vitro stimulation with A20 cells." (PMID 32974162, 2020). "Other multiple microenvironment-based factors, such as immune checkpoints expression, proportion of tumor infiltration lymphocytes (TIL), and interferon gamma (IFNγ) signature, also play vital roles in response to immunotherapy." (PMID 32491995, 2020).
tumor (continued). "Interleukin (IL)-1β and interferon gamma (IFNγ) activate STAT1 to produce ARG1 and inducible nitric oxide synthase (iNOS) and suppressive cytokines such as TGFβ to play a role in promoting tumor growth." (PMID 32325683, 2020). "Administration of a BTK inhibitor also reduced tumor burden and increased CD8 T cell production of IFNγ in an orthotopic mouse model." (PMID 33584701, 2020). "Knockdown of IL-1β decreased tumor growth and reversed TAM immune suppression while increasing the frequency of polyclonal CD8 T cells and their production of IFNγ and Granzyme B." (PMID 33584701, 2020). "The anti-tumour positive immunomodulatory change is more discerned in terms of Tregs, CD8+ T cells, TGF-β, IFNγ, IL-10 and IL-17 respectively." (PMID 32466214, 2020). "Although IFNγ production has been shown to inhibit angiogenesis, these results highlight a mutual positive regulation between CD4+ T cells and tumor vessel normalization." (PMID 33096748, 2020). "For example, in cancer, interferon gamma (IFN-γ), one of the two main anti-tumor effector cytokines produced by activated CD8+ T cells, is suppressed by tumor necrosis factor receptor 2 positive (TNFR2+) Tregs." (PMID 32093265, 2020). "We found that early intratumoral accumulation of interferon gamma (IFN-γ)-producing natural killer (NK) cells induced a profound remodeling of the TME and unleashed cytotoxic T cell (CTL)-mediated tumor eradication." (PMID 33220234, 2020). "DC-loaded with A7450 T1 M1 tumor lysate boosted the frequency of CD3+CD8+ T cells, which were activated and additionally positive for IFNγ." (PMID 33087163, 2020). "Although vaccination with both human ESCs and iPSC lines induced significant expansion of tumor-specific IFNγ- and IL-4-producing T cells, only human ESC cells inhibited tumor growth." (PMID 33266109, 2020). "Quantification of CD8 TIL functional capacity from CON NT, CON + anti-PD-1, ACA NT, and ACA + anti-PD-1 revealed respective stepwise increases in the frequencies of IFNγ+ TNFα+, and perforin+ CD8 T cells within the tumor microenvironment." (PMID 33036247, 2020). "To investigate the effect of HO-1 on tumor-related inflammation, we measured the concentration of IL-6, IL-10, IL-12, MCP-1 and IFNγ in serum using the BDTM CBA Mouse Inflammation kit." (PMID 33287312, 2020). "Thus, in addition to factors such as microsatellite stability status, tumor mutational burden, and expression of checkpoint inhibitory molecules, high IFNγ expression levels could potentially be investigated as a predictive biomarker for the potential for immune responsiveness of a tumor." (PMID 32265897, 2020). "The natural killer (NK) cells that infiltrated into the tumor lesions expressed higher levels of CXC chemokine receptor 3 (CXCR3), as these cells expressed lower levels of interferon-γ (IFNγ)." (PMID 32457755, 2020). "Agonistic CD40 mAb treatment substantially increased the expression of IFNγ and IDO1 in tumor tissue, and their levels in individual tumors were positively correlated." (PMID 32231867, 2020). "Consistent with a requirement for T-cell responses in the observed tumor suppressive effects by anti-PD-L1 blockade, both activated CD69+/CD8+ and IFNγ+/CD8+ T cells correlated with changes in survival in the different treatment groups." (PMID 32075966, 2020). "Upon activation, T-cells produce IFNγ which increases antigen spread and further enhances MHC expression on tumour cells, augmenting immune recognition." (PMID 33148287, 2020). "Specifically, Carma1, Rel, Nrp1, Ezh2, Senp3, and Ikzf2-null Treg all produce appreciable amounts of IFNγ and/or TNF in the tumor microenvironment." (PMID 33143070, 2020). "We confirmed these findings using ex vivo isolated and short-term expanded bulk tumor-specific CTL lines from four cancer patients and demonstrated that IFNγ methylation inversely correlates with transcription, protein level, and cytotoxicity." (PMID 32194559, 2020).